ENSG00000283228 (novel transcript)
Gene: Protein-coding gene on chromosome 2 (151,802,651 to 151,973,949, reverse strand). Ensembl gene ENSG00000283228.
Genetic constraint (gnomAD): Missense variants: 130 observed, 187.96 expected, observed/expected ratio (o/e) 0.69, 90% interval 0.6 to 0.8. Synonymous variants: 65 observed, 71.32 expected, observed/expected ratio (o/e) 0.91, 90% interval 0.75 to 1.12.